NLRP3 (NLR family pyrin domain containing 3)
Diseases named in the same sentence as NLRP3 in open-access papers (continued):
Sharing a sentence is not in itself a finding about the gene and the disease.
diabetes (continued). "Therefore, our results implicate H3 relaxin as a potential therapeutic strategy for ameliorating NLRP3 inflammasome activation related to HG‐induced cardiac fibrosis in diabetes." (PMID 29314607, 2018). "Sustained activation of NLRP3 inflammasome is closely related to diabetes and stroke." (PMID 29853850, 2018). "Hence, we elucidated a novel mechanism in which P2X7R‐mediated NLRP3 inflammasome activation is inhibited by H3 relaxin in the pathogenesis of diabetes." (PMID 29314607, 2018). "Moreover, NLRP3 inflammasome is also involved in the development of myocardial dysfunction with sepsis and diabetes in animal models." (PMID 29371912, 2017). "There are few reports on the NLRP3 inflammasome in patients with diabetes with CAS." (PMID 29151018, 2017). "Recent studies have suggested NLRP3 inflammasome/IL-1β pathway plays a critical role in the pathogenesis of type 2 diabetes mellitus, and other evidences have previously shown that sustained NLRP3 inflammasome activity contributes to impairing wound healing in diabetic mice." (PMID 28164132, 2017). "NLRP3 inflammasome-mediated IL-1β production from infiltrating macrophages within the pancreas can contribute to the death of pancreatic β-cell and subsequent diabetes." (PMID 29230270, 2017). "Our present study investigated whether diabetes aggravated MI/R injury through NLRP3 inflammasome-mediated pyroptosis." (PMID 29062465, 2017). "In particular, the NLRP3 inflammasome as an important sensor is involved in the vascular endothelial pathological process, which assembly activate caspase-1 leading to the processing of bio-active IL-1β secretion in diabetes." (PMID 29207644, 2017). "In this study, we investigated the reno-protective effect of PIO in apolipoprotein E (apoE)-knockout (-/-) mice with diabetes, with a particular emphasis on the relationship between PIO and alterations in NLRP3 inflammasome activation, as well as the underlying mechanisms." (PMID 28708885, 2017). "Herein, we examined the impact of diabetes mellitus on thioredoxin-interacting protein (TXNIP) expression and whether mediated NLRP3 activation was associated with renal ischemia/reperfusion- (I/R-) induced AKI." (PMID 27867451, 2016). "Thus, activation of the NLRP3 inflammasome is required for diabetes to induce prolonged QTc and arrhythmias." (PMID 27882934, 2016). "Moreover, the mRNA and protein levels of NLRP3 inflamamsome components and IL-1β achieved the highest levels at 8 or 12 weeks of diabetes except pro-IL-1β (all p<0.01)." (PMID 25136835, 2014). "The decrease of cardiac NLRP3 inflammasome in late stage of diabetes might be due to the adaptive protection of myocardium under the consistent stimuli in diabetes." (PMID 25136835, 2014). "Initial studies in humans suggest that NLRP3 inflammasome activation in obesity could be important in development and treatment of insulin-resistance and diabetes." (PMID 23483669, 2013). "Consistent with relevance of this pathway in diabetes treatment, Il-1β, Nlrp3, and Asc gene expression is reduced after 1 year of weight loss in obese type 2 diabetic patients, and these gene expression changes were positively correlated with improvements in glycemia." (PMID 23483669, 2013). "These mice are also protected against insulin resistance and metabolic dysfunction during obesity-induced diabetes, depicting that the NLRP3 inflammasome may function as a sensor that detects danger signals and provokes inflammatory reaction in these diseases." (PMID 23825667, 2013). "Considering that the pancreatic damage that occurs during diabetes is an ongoing inflammatory process that may not be readily reversible, an early preventive strategy targeting NLRP3 inflammasome may prove useful in diabetes and its complications." (PMID 23483669, 2013). "However, whether NLRP3 inflammasome is involved in diabetes-induced fibroblast pyroptosis in diabetic wound tissues remains unclear." (PMID 40936902, 2025).
diabetes (continued). "However, in studies of type 2 diabetes caused by hepatitis C virus infection, it is shown that KCNQ1OT1 was found to promote the scorch death of β-cells infected by hepatitis C virus through the miR-223-3p/NLRP3 axis, thereby affecting insulin production and accelerating the onset of diabetes and." (PMID 41334450, 2025). "Furthermore, in db/db mice, the hyperglycemic environment of diabetes stimulates microglia to produce reactive oxygen species and activates the NF-κB/NLRP3 signaling pathway, leading to the production of NLRP3 inflammasome (e.g., IL1β, IL6, and IL18), which in turn mediates cognitive dysfunction." (PMID 40948877, 2025). "The NLRP3 gene plays a crucial role in the pathophysiology and progression of diabetes mellitus (DM)." (PMID 40562805, 2025). "Acting as a vital adapter protein, it skillfully assembles with notable partners such as NLRP3 and procaspase-1 to detect metabolic stress signals—including free fatty acids, cholesterol, and islet amyloid polypeptide —substances all too common in the landscape of diabetes." (PMID 41296433, 2025). "Importantly, aerobic exercise was unveiled to activate irisin, thereby inhibiting NLRP3/IL-18 and its subsequent inflammatory response and glycolipid metabolism, which provides effective approaches for the management of diabetes by using aerobic exercise intervention." (PMID 41264598, 2025). "Furthermore, upregulation of the NLRP3 and IL-1β genes can influence upon chronic inflammation, potentially affecting the function of the endocrine system, possibly contributing to metabolic problems such as obesity, insulin resistance and diabetes." (PMID 39264098, 2024). "Thus, the outcomes of the current study could provide insights into the identification of new potential NLRP3 inflammasome inhibitors against diabetes and its related disorders." (PMID 38637900, 2024). "Since pharmacological targeting of the NLRP3 inflammasome alleviates pancreatic inflammation and β-cell death in preclinical models, small molecules targeting IRE1α RNase activity and/or the NLRP3 inflammasome could be attractive strategies in diabetes and chronic metabolic diseases." (PMID 38744890, 2024). "Studies from the field of Diabetes Mellitus (DM) directly link NLRP3 and CGRP-related pathways, where NLRP3 activation (e.g., via reactive oxygen species) and consequent IL-1β production have been shown to affect receptor resistance and apoptosis in DM models." (PMID 39568667, 2024). "The P2X7R/NLRP3/IL‐1β signaling pathway may play an important role in the antidepressant‐like behavior of taVNS, which provides a promising mechanism for taVNS clinical treatment of diabetes combined with depression." (PMID 38752512, 2024). "Therefore, it can be speculated that Allicin might be also an inhibitor of NLRP3 inflammasome in cardiac injury and hypertrophy induced by diabetes and pathological overload, which needs further investigation." (PMID 37596540, 2023). "The amount of NLRP3 transcripts may be low under healthy conditions and may increase only upon certain stimuli, therefore we first analyzed kidneys from individuals with diabetes and “diabetic kidney disease”." (PMID 37744356, 2023). "Furthermore, the NLRP3 inflammasome plays an important role in the development of abdominal aortic aneurysm, myocardial damage in ischemia-reperfusion injury, kidney damage in diabetes, gout, and acute renal failure." (PMID 36768404, 2023). "However, whether NLRP3 could mediate the occurrence and development of diabetes by mediating the less severe pre-diabetic state is poorly understood." (PMID 36817440, 2023). "However, although the importance of NLRP3 in diabetes has been established in animal and human models, the expression profiling of NLRP3 inflammasome in pre-diabetic subjects remains largely unknown." (PMID 36817440, 2023). "However, evidence linking NLRP3 inflammasome and pre-diabetes has been scarcely explored." (PMID 36817440, 2023).
diabetes (continued). "Next, to determine whether NLRP3 inflammasome is involved in the regulation of pre-diabetes and exercise on systemic insulin sensitivity, we performed correlation analysis between the protein levels of NLRP3 inflammasome components and the value of HOMA-IR in the whole samples." (PMID 36817440, 2023). "In diabetes, hyperglycemia-induced oxidative stress due to myocardial mitochondrial perturbations triggers inflammatory signaling factors, such as nuclear factor-κB (NF-κB) and NLRP3 inflammasome, which contribute to the severity of MI-related injury, adverse cardiac remodeling, and heart failure." (PMID 37240345, 2023). "In a hyperglycemic environment, reactive oxygen species (ROS) activate NLRP3 inflammatory vesicles in pancreatic β-cells, promoting IL-1β secretion leading to insulin secretion dysfunction, promoting obesity and insulin resistance, and ultimately inducing type 2 diabetes mellitus raw." (PMID 37443131, 2023). "In addition to NAD+ depletion, the increased expression of CD38 in diabetes involves the release of intracellular cADPR-mediated Ca2+ and mitochondrial damage, resulting in Nlr family pyrin domain-containing 3 (Nlrp3) inflammasome activation, VSMC proliferation and collagen I synthesis." (PMID 36831262, 2023). "However, it is still rather unclear whether NLRP3 inflammasome activation is regulated by TLR4 during CIRI in the context of diabetes." (PMID 35419168, 2022). "Hence, potato-derived flavonoids have been described to prevent NLRP3 inflammasome activation, probably as a consequence of decreased ROS formation, and to attenuate premature endothelial cell senescence in an in vivo model of diabetes induced by D-galactose." (PMID 35204152, 2022). "Recently, the research community has come to understand that diabetes produces a systemic state of low-level inflammation known as meta-inflammation and attention has focused on a role for the sterile inflammation-inducing structure known as the NLRP3 inflammasome." (PMID 36505062, 2022). "In addition, we will highlight some current therapeutic strategies targeting the NLRP3 inflammasome signaling pathway, which may provide new targets for treating diabetes." (PMID 36387904, 2022). "Furthermore, ER stress also plays an important role by regulating NLRP3 inflammasomes in diabetes; hence, whether exogenous H2S can improve diabetes by regulating ER stress/NLRP3 inflammasomes is a subject worth studying in the future." (PMID 35806174, 2022). "Additionally, the protective effect of N-acetylcysteine (NAC) in diabetes-related ocular surface damage may be attributed to inhibition of the ROS/NLRP3/Caspase-1/IL-1β pathway." (PMID 35656447, 2022). "Our study elucidated that HG induced Golgi stress was mediated by NLRP3/Vps35/Golph3/Vimentin pathway, inhibition of NLRP3 and Golph3 by selected molecular inhibitors zafirlukast and bromocriptine could suppress neuro-inflammation and Golgi stress thus ameliorate diabetes cognitive decline." (PMID 36378718, 2022). "Furthermore, TXNIP can be induced by ROS, leading to NLRP3 activation in diabetes." (PMID 36017183, 2022). "NLRP3 inflammasome inhibition by MCC950 could improve diabetes-mediated cognitive impairment." (PMID 36238294, 2022). "Moreover, rosuvastatin could suppress NLRP3 inflammasome and IL-1β release in rats with type 2 diabetes and alleviate diabetes-induced cardiac dysfunction." (PMID 35017318, 2022). "Therefore, based on effective control of blood glucose, NLRP3 inflammasome and its related inflammatory factors may become important targets for Tai Chi intervention to ameliorate pre-diabetes." (PMID 36248820, 2022). "This study evaluated whether empagliflozin (EMPA) protects the pancreas from diabetes mellitus-induced injury by downregulating the nucleotide-binding oligomerization domain-like receptor protein 3 (NLRP3)/caspase-1/Gasdermin D (GSDMD) pyroptosis-related inflammasome pathway in vitro and in vivo." (PMID 34823419, 2021).
diabetes (continued). "Collectively, it can be inferred that metformin and resveratrol ameliorate adipose dysfunction through inhibiting ERS-induced NLRP3 inflammasome and Drp1-mediated mitochondrial fission, which may be an effective treatment strategy for adipose dysfunction in diabetes." (PMID 33937267, 2021). "Lastly, we speculate a reasonable link of NLRP3 inflammasome between diabetes and CCS." (PMID 34512671, 2021). "Thus, NLRP3 may be a novel therapeutic target to alleviate inflammasome hyperactivation in patients with diabetes." (PMID 34294853, 2021). "However, NLRP3 may be activated by chronic inflammation in diabetes, becoming pathologic and promoting disease." (PMID 34997893, 2021). "Therefore, whether H2S can improve diabetes through regulating ERS/NLRP3 inflammasome is a subject worth studying." (PMID 33937267, 2021). "However, it is unclear whether NLRP3 inflammasome is involved in stroke-induced retinal injury in diabetes." (PMID 34305534, 2021). "Moreover, the NLRP3 inflammasome can regulate autophagy to play a role in diabetes." (PMID 34201520, 2021). "In addition, it has been found that NLRP3 inflammasome is activated in rat models of diabetes mellitus, which may aggravate MI/R injury by mediating myocardial cell apoptosis." (PMID 34422094, 2021). "Of note, isoflurane pretreatment inhibited the NLRP3 inflammasome activation in the retina, indicating that isoflurane pretreatment may provide substantial retinal protection in stroke-induced retinal injury in diabetes." (PMID 34305534, 2021). "Moreover, related research on NLRP3 inflammasomes and P2X7 receptors is summarized and used as a reference for confirming that the excessive activation of P2X7- NLRP3 leads to the increased release of inflammatory cytokines, such as IL-1β, in depression and diabetes." (PMID 32166013, 2020). "So, we hypothesize that the pre-existing hyperactivation of NLRP3 inflammasome, hypercytokinemia, chronic inflammation and increased vascular permeability in uncontrolled diabetes could be major contributing factors for the development of severe COVID-19 complications." (PMID 33329516, 2020). "Therefore, the activation of NLRP3 inflammasomes by P2X7 receptors may be an important pathogenesis of diabetes." (PMID 32166013, 2020). "Similarly, given the relevance of inflammatory mediators, and particularly IL-1β, in the pathophysiology of diabetes and diabetic cardiomyopathy, targeting the NLRP3/IL1β pathway could effectively reduce the burden of this disease." (PMID 31652822, 2019). "However, it is unknown whether aldosterone induces vascular dysfunction and complications in diabetes via NLRP3 inflammasome activation." (PMID 31817997, 2019). "Moreover, the inhibition of NLRP3 inflammasome activation can alleviate diabetic complications, including diabetic cardiomyopathy, diabetic nephropathy, diabetic retinopathy, diabetes-related wound-healing defects, and diabetic vascular endothelial dysfunction." (PMID 29507694, 2018). "The latest studies have shown that careful targeting of NLRP3 signaling pathways could be beneficial for the treatment of diabetes mellitus and diabetic nephropathy, so the NLRP3 inflammasome should be a new potential target for the treatment of diabetic nephropathy." (PMID 28182085, 2017). "However, the role of pyroptosis induced by ROS-mediated NLRP3 inflammasome activation in hyperglycaemia or hypoxia-induced cardiomyocyte death in diabetic status and whether diabetes-aggravated MI/R injury is related to pyroptosis are unclear." (PMID 29062465, 2017). "Therefore, we hypothesized that pyroptosis induced by ROS-mediated NLRP3 inflammasome activation plays a fundamental role in the severity of MI/R injury in diabetes." (PMID 29062465, 2017). "Intriguingly, the cardiac NLRP3 inflammasome and IL-1β expression in DM group were increased at 4 weeks, and reached to the highest levels at 8 or 12 weeks, and maintained at moderate high levels until 20 weeks of diabetes." (PMID 25136835, 2014).
diabetes (continued). "A growing literature has demonstrated that the formation of a multi-protein NLRP3 inflammasome signaling complex and subsequent cytokine activation is an underlying mechanism of VAT and pancreatic inflammation contributing to metabolic dysfunction and diabetes." (PMID 23924318, 2013). "This activation was confirmed by the increased expression of NLRP3, caspase-1, GSDMD, and IL-1β, suggesting the involvement of NLRP3 inflammasome in diabetes-induced periodontal pathology." (PMID 41596771, 2026). "NLRP3/IL-6/IL-1/TNF-α expression was reduced, and diabetes/hyperglycaemia-induced oxidative stress was suppressed, as evidenced by decreased 8-isoprostane and elevated superoxide dismutase-2 levels in vitro and in vivo." (PMID 41214779, 2025). "It is worth noting that the NLRP3 inflammasome was significantly activated in the renal tissue of UUO mice and in those with streptozotocin-induced diabetes." (PMID 40830103, 2025). "Taken together, these findings suggest that inflammasomes, including NLRP3, AIM2, NLRP1, NLRP6 and NLRC4 inflammasomes are involved in the regulation of insulin resistance, pancreatic β-cell health and diabetes." (PMID 40433411, 2025). "SIRT1 expression was found to be low in mice with STZ-induced diabetes, but puerarin increased SIRT1 expression, inhibited the activation of the NLRP3/caspase 1 pathway, reduced podocyte pyroptosis, and alleviated their renal inflammatory injury." (PMID 41020857, 2025). "Drugs such as glyburide, a sulfonylurea used in diabetes treatment, and brilliant blue G, an antagonist of P2X purinergic receptor 7 (P2X7) receptors, have been shown to inhibit the activation of NLRP3 and reduce the secretion of pro-inflammatory cytokines." (PMID 40943287, 2025). "AgNP+18β‐GA improved sperm morphology and histopathological damage in diabetes‐induced testicular damage, as well as inhibited P2X7 receptor and endoplasmic reticulum stress‐mediated NLRP3 inflammasome activation." (PMID 41280745, 2025). "The activated LRR region inhibits NLRP3 inflammasome activation through NEK7-NLRP3 complex with NIMA-related kinase 7 (NEK7), which plays an important role in AS, diabetes, Alzheimer's disease, and inflammatory bowel disease." (PMID 39742016, 2024). "Compared with the normal control group, the mRNA levels of NLRP3, NFE2L2, and NFKB1 in the diabetes model group were significantly increased, while they decreased in the SAL treatment group (P < 0.05), with the statistical difference." (PMID 38243268, 2024). "Our previous studies showed that FGF21 downregulates NLRP3 inflammasome activity, inhibits VSMC proliferation and migration, and alleviates diabetes-aggravated neointimal hyperplasia." (PMID 38733164, 2024). "Nod-like receptor protein 3 (NLRP-3), is an intracellular sensor that is involved in inflammasome activation, and the aberrant expression of NLRP3 is responsible for diabetes mellitus, its complications, and many other inflammatory diseases." (PMID 38637900, 2024). "The authors observed that the excessive ROS presence in diabetes promoted an OxInflammation environment, intensifying TGF-beta’s downregulation and NLRP3’s upregulation, which are critical wound healing pathways." (PMID 39201678, 2024). "Beyond its role in diabetes therapy, metformin also mitigates ischemia-reperfusion injury by dampening cardiomyocyte pyroptosis through the AMPK/NLRP3 pathway." (PMID 39201755, 2024). "Thus, NLRP3 inflammasome activation may be correlated with pyroptosis in diabetes." (PMID 36648717, 2023). "Treatment with metformin prevents TXNIP/NLRP3 inflammasome activation by suppressing ER stress in the adipose tissues of STZ-injected diabetic mice, thereby blocking diabetes-induced adipose dysfunction." (PMID 37394581, 2023). "Hyperglycemia, a diabetes-related endogenous DAMP, can provide a priming signal in NLRP3 inflammasome activation, increasing the transcription of the IL-1β gene and, ultimately, the secretion of pro-ILs." (PMID 37238986, 2023).